CPXM1 (carboxypeptidase X, M14 family member 1)
Description:
May be involved in cell-cell interactions. No carboxypeptidase activity was found yet (By similarity).
Synonyms: CPX1; CPXM; CPX-1
Tractability: Antibody: UniProt places it where antibodies can reach, with medium confidence; UniProt predicts a signal peptide or a membrane-spanning region; its Gene Ontology location is reachable by antibodies, with medium confidence. PROTAC: ubiquitination databases record sites on it.
Gene: Protein-coding gene on chromosome 20 (2,794,069 to 2,800,658, reverse strand). Ensembl gene ENSG00000088882.
Subcellular location: Secreted
Gene Ontology:
Molecular function: metallocarboxypeptidase activity; zinc ion binding
Biological process: proteolysis
Cellular component: extracellular region
Genetic constraint (gnomAD): Loss-of-function variants: 72 observed, 81 expected, observed/expected ratio (o/e) 0.89, 90% interval 0.73 to 1.08. The upper end of that interval is the gene's LOEUF score, 1.08, which puts it in group 4 of 6, group 1 being the genes least tolerant of losing a copy. Missense variants: 892 observed, 985.02 expected, observed/expected ratio (o/e) 0.91, 90% interval 0.86 to 0.96. Synonymous variants: 403 observed, 396.12 expected, observed/expected ratio (o/e) 1.02, 90% interval 0.94 to 1.11.
Homologues: Orthologues: chimpanzee CPXM1 (99% identical), macaque CPXM1 (97% identical), pig CPXM1 (89% identical), dog CPXM1 (89% identical), rabbit CPXM1 (88% identical), guinea pig CPXM1 (87% identical), rat Cpxm1 (86% identical), mouse Cpxm1 (85% identical), tropical clawed frog ebf4 (59% identical), zebrafish cpxm1b (57% identical), zebrafish cpxm1a (54% identical). Paralogues in human: CPXM2 (50% identical), AEBP1 (47% identical), CPD (31% identical), CPZ (30% identical), CPN1 (28% identical), CPE (28% identical), CPM (20% identical).
Diseases named in the same sentence as CPXM1 in open-access papers:
CPXM1 is named in the same sentence as 24 diseases in open-access papers, as found by Europe PMC text mining. Sharing a sentence is not in itself a finding about the gene and the disease. The quoted sentences say what the papers report.
breast carcinoma (6 papers, 2018 to 2025). "While its role in cancer remains largely undefined, CPXM1 has been reported to be hypermethylated and downregulated in breast cancer." (PMID 37958445, 2023). "An elevated methylation status in the CPXM1 promoter region in breast cancer tissues relative to normal tissues has been reported, and elevated CPXM1 expression has been linked with extended survival." (PMID 37958445, 2023). "Among the 4 genes, RASGRF1 and CPXM1 represented common breast cancer marker, while HOXA10 and DACH1 represented luminal-dominant marker and triple negative dominant marker, respectively." (PMID 32550045, 2020). "A study exploring epigenetic markers of breast cancer—utilizing breast cancer tissues, breast cancer cell lines, and blood samples from healthy participants—proposed that the expression of CPXM1 is epigenetically controlled, potentially functioning as a tumor suppressor gene in breast cancer cells." (PMID 37958445, 2023). "Methylation pattern of MAST1, PRDM14, and ZNF177 may represent new diagnostic biomarkers for breast cancer, while methylation of ADCY4, CPXM1, DNM3, PRDM14, PRKCB, and ZNF177 may hold prognostic potential for breast cancer." (PMID 33499882, 2021). "There is experimental evidence indicating that expression of CPXM1 is epigenetically regulated in breast cancer and it may act as a tumor suppressor gene." (PMID 30072699, 2018). "The CPXM1 gene may be involved in adipogenesis and extracellular matrix remodelling and it has been suggested to be a tumour suppressor in breast cancer." (PMID 30072699, 2018). "As expected, methylation levels of ADCY4, CPXM1, DNM3, GNG4, MAST1, PRDM14, and ZNF177 were found to be increased in breast cancer, and all with p values lower than 0.001." (PMID 33499882, 2021). "To further explore the clinical value of these biomarkers, we evaluated whether 6 of our differentially methylated genes—ADCY4, CPXM1, DNM3, PRDM14, PRKCB, and ZNF177—had any relation with overall survival of breast cancer patients." (PMID 33499882, 2021). "It is interesting to mention that four methylation markers (RASGRF1, CPXM1, HOXA10, and DACH1) in circulating cell-free DNA could discriminate cancer from normal with high sensitivity (0.86) and specificity (0.83) in early breast cancer." (PMID 32550045, 2020). "Moreover, we showed that DNA methylation landscape of ADCY4, CPXM1, DNM3, PRDM14, PRKCB, and ZNF177 could be selected as accurate biomarkers for the prognosis of breast cancer." (PMID 33499882, 2021).
head and neck squamous cell carcinoma (3 papers, 2023 to 2024). A squamous cell carcinoma that arises from any of the following anatomic sites: lip and oral cavity, nasal cavity, paranasal sinuses, pharynx, larynx, and salivary glands. "CPXM1, a putative tumor suppressor gene, was found to have a positive relationship with immunotherapy in head and neck squamous cell carcinoma." (PMID 36450891, 2023). "Interestingly, a recent study demonstrated that an immune-related gene prognostic index constructed using SFRP4, CPXM1, and COL5A was associated with better survival and better responses to immune checkpoint inhibitor therapy for head and neck squamous cell carcinoma." (PMID 38664626, 2024). "A prognostic index built from a trio of genes, inclusive of CPXM1, correlated with responsiveness to immune checkpoint inhibitors (ICI) in head and neck squamous cell carcinoma." (PMID 37958445, 2023).
gastric cancer (2 papers, 2025). A primary or metastatic malignant neoplasm involving the stomach. "The CpG site cg06539804 affects the methylation of the CPXM1 gene, which is upregulated in gastric cancer and correlated with poor prognosis." (PMID 40177272, 2025).
leukemia (2 papers, 2022 to 2026). A malignant (clonal) hematologic disorder, involving hematopoietic stem cells and characterized by the presence of primitive or atypical myeloid or lymphoid cells in the bone marrow and the blood. "A previous study showed that CPXM1 is closely associated with leukemia stem cells and can be used as a prognostic gene in patients with acute myeloid leukemia (AML) and myelodysplastic syndrome (MDS)." (PMID 36407095, 2022).
melanoma (2 papers, 2022 to 2023). A malignant, usually aggressive tumor composed of atypical, neoplastic melanocytes. "In the context of melanoma, a gene panel encompassing CPXM1 was discerned as a predictive tool for anti-PD-1 therapy response." (PMID 37958445, 2023). "Using WGCNA combined with supervised machine learning algorithms, we identified a novel CAFs-related panel, including six genes (CDK14, SYNPO2, TCF4, GJA1, CPXM1, TFPI), which can distinguish the response of melanoma patients under anti-PD-1 immunotherapy." (PMID 35479936, 2022).
serous ovarian cancer (2 papers, 2021 to 2024). "CPXM1 was also included in a tumor microenvironment prognostic signature profile comprised of 11 immune checkpoint genes for advanced-stage serous ovarian cancer." (PMID 38664626, 2024).
bladder cancers (1 paper, 2023). "We also found that CPXM1 is aberrantly methylated and downregulated in human bladder cancers and human bladder cancer cells." (PMID 37958445, 2023). "Furthermore, CPXM1 is aberrantly methylated and downregulated in human bladder cancers and human bladder cancer cells." (PMID 37958445, 2023).
glaucoma (1 paper, 2025). Increased pressure in the eyeball due to obstruction of the outflow of aqueous humor. "Among them, CPXM1 (OR: 0.53, 95% CI: 0.39 − 0.73, P < 0.001) and FLT4 (OR: 0.86, 95% CI: 0.78 − 0.95, P = 0.005) exhibited associations with glaucoma consistent with those of the corresponding proteins." (PMID 40635100, 2025). "By using a comprehensive analysis pipeline, we identified five potential therapeutic targets for glaucoma: two tier 1 genes (CPXM1 and FLT4), one tier 2 gene (INSR), and two tier 3 genes (CPZ and PXDN)." (PMID 40635100, 2025). "The protective effect of CPXM1 against glaucoma could be attributed to its IOP-lowering role according to our glaucoma endophenotypes validation." (PMID 40635100, 2025). "CPXM1, another candidate target gene with tier 1 evidence for association with glaucoma and tier 3A evidence for druggability, has not been extensively studied." (PMID 40635100, 2025). "Among actionable druggable genes, CPXM1 and FLT4 exhibited protective roles in glaucoma, supported by tier 1 evidence." (PMID 40635100, 2025).
Hypertension (1 paper, 2023). The presence of chronic increased pressure in the systemic arterial system. "Furthermore, PIK3C2G, FIBIN, CHRNA1, NPNT, MEOX1, and POU2F2 linked obesity and lung cancer, while PTPRQ, SSUH2, CILP2, CDH2, ABCA12, CPXM1, and L1CAM linked hypertension and lung cancer." (PMID 36685671, 2023).
osteoporosis (1 paper, 2025). A condition of reduced bone mass, with decreased cortical thickness and a decrease in the number and size of the trabeculae of cancellous bone (but normal chemical composition), resulting in increased fracture incidence. "By leveraging bidirectional two-sample MR analysis, we identified CPXM1 (Carboxypeptidase X, M14 family member 1) as a novel gene that is causally linked to osteoporosis risk." (PMID 41029778, 2025). "Our multi-omics MR framework, integrating RNA-seq, eQTL, and pQTL data, identified CPXM1 as a novel causal mediator of osteoporosis risk." (PMID 41029778, 2025). "COL6A2 and CPXM1, both associated with extracellular matrix composition and remodeling, were found to increase susceptibility to osteoporosis, whereas SPARC exhibited a protective effect, consistent with its known roles in bone matrix mineralization and osteoblast function." (PMID 41029778, 2025). "The concordant risk effects observed across both eQTL and pQTL analyses (P < 0.05), coupled with the absence of genome-wide pleiotropy in PheWAS (P < 5 × 10−8), underscore CPXM1 as a prioritized therapeutic target for osteoporosis." (PMID 41029778, 2025). "After log2 transformation and quantile normalization, differential expression analysis using DESeq2 revealed significant upregulation of CPXM1 in osteoporosis patients." (PMID 41029778, 2025). "In conclusion, our study presents CPXM1 as a promising drug target for osteoporosis, leveraging a multi-omics MR approach to uncover novel molecular insights." (PMID 41029778, 2025). "Given that osteoporosis was characterized by reduced bone mineral density and increased bone fragility, often associated with abnormal bone matrix degradation and remodeling, CPXM1 could play a significant role in regulating bone strength and density by modulating these processes." (PMID 41029778, 2025). "By integrating cis-eQTL, pQTL, and RNA-seq data, four candidate genes were identified with significant causal effects on osteoporosis risk, including COL6A2, CPXM1, MGP, and SPARC." (PMID 41029778, 2025). "Although research on CPXM1’s direct involvement in bone metabolism, particularly in osteoporosis, is still limited, its role in bone matrix remodeling is of increasing interest." (PMID 41029778, 2025). "Further validation and clinical trials will be critical in assessing the efficacy and safety of targeting CPXM1 in osteoporosis treatment." (PMID 41029778, 2025). "To validate the role of CPXM1 in osteoporosis, we analyzed RNA-seq data from MSCs isolated from femoral head bone marrow of elderly osteoporosis patients and age-matched non-osteoporotic controls (GSE35958)." (PMID 41029778, 2025). "Collectively, these findings highlight the viability of Doxorubicin, 5-Fluorouracil, and 2-Methylcholine as therapeutic candidates targeting CPXM1 in osteoporosis, warranting further preclinical and clinical investigations to assess their efficacy and safety in this context." (PMID 41029778, 2025). "In our investigation using the DSigDB drug database, we identified promising drug candidates that may target CPXM1 for osteoporosis treatment." (PMID 41029778, 2025). "Overall, while more research is required, CPXM1’s potential role in bone metabolism and osteoporosis is a promising area for future investigation, as it could lead to new therapeutic targets for osteoporosis treatment." (PMID 41029778, 2025). "Finally, computational drug repurposing predicted several promising drug candidates, including Doxorubicin, 5-Fluorouracil, and 2-Methylcholine, which may target CPXM1 pathways for osteoporosis treatment." (PMID 41029778, 2025).
polycystic ovary syndrome (1 paper, 2024). A disorder that manifests as multiple cysts on the ovaries. "An increase in CPXM1 expression in the adipose tissue of obese mice and humans suggested a key role in adipogenesis, while increased CPXM1 expression in a mouse model of polycystic ovary syndrome suggested a role in the ovary as well." (PMID 39050735, 2024).
Stroke (1 paper, 2012). Sudden impairment of blood flow to a part of the brain due to occlusion or rupture of an artery to the brain. "New stroke-genes involved presumably in extracellular matrix remodelling included the transiently upregulated carboxipeptidase-encoding Cpxm1 and the permanently upregulated epithelial membrane protein 3 (Emp3)." (PMID 23251410, 2012).
cancer (9 papers, 2010 to 2025). A tumor composed of atypical neoplastic, often pleomorphic cells that invade other tissues. "We only found two other missense variants in the entire CPXM1 gene in three different families out of the 77 cancer families, each present either in only one case or only one control of the family." (PMID 30072699, 2018). "CPXM1 is suggested as an immune-related gene to predict cancer prognosis, which is consistent with our findings." (PMID 35479936, 2022). "CPXM1 was demonstrated to be involved in adipogenesis, osteoclastogenesis, and cancer." (PMID 34916661, 2022). "Literature search gave some evidence about a potential function of the CPXM1 gene in cancer." (PMID 30072699, 2018). "Although one study reported that CPXM1 may regulate osteoclastogenesis in mice, its function in human cancer cells remains unknown." (PMID 27993161, 2016). "Although these reports do not delve into the intricate role of CPXM1 in cancer, epidemiological findings suggest its expression in malignancies is correlated with prognosis and ICI responsiveness." (PMID 37958445, 2023). "Although CPXM1, CCL4, ZBTB10 and B3GNT2 have not been reported to be related to the prognosis of ALL, the four genes we screened are all closely related to cancer, and we have reason to believe that they may also be potential genes for predicting the prognosis of ALL." (PMID 36407095, 2022).
tumor (9 papers, 2018 to 2025). "Additionally, rs215539 (r = 0.501, p = 0.004) in CPXM1, which is associated with tumor progression and immune cell infiltration, and rs1332664 (r = 0.484, p = 0.005) in CFHR5, a gene related to complement regulation, were also significantly associated with general fatigue." (PMID 40462080, 2025). "CPXM1 may serve as a tumour suppressor in breast cancer, potentially through involvement in adipogenesis or extracellular matrix remodelling, and it is reported to be down-regulated by a lncRNA in PTC45." (PMID 30072699, 2018). "The other molecules, including IFN-γ, CXCL, CTLA-4, MTAP, SFR4/CPXM1/COL5A1, TILs, CAFs, exosomes, and peripheral blood indicators, may have suggestive significance for tumor immune microenvironment and prognosis of immunotherapy." (PMID 36860322, 2023). "Moreover, tissue microarray outcomes from human UCs indicated a pronounced reduction in CPXM1 expression in UCs, irrespective of T-stage, tumor grade, or gender." (PMID 37958445, 2023).
CPXM1 also shares sentences with these, for which no sentence is quoted: myelodysplastic syndrome (2 papers); acute myeloid leukemia (1); asthma (1); astrocytomas (1); glucose metabolism disorder (1); infection (1); Insulin resistance (1); lung carcinoma (1); Obesity (1); ovarian carcinoma (1).